PRRC1 (proline rich coiled-coil 1)
Description:
May act as a regulator of the protein kinase A (PKA) activity during embryonic development.
Synonyms: FLJ32875
Tractability: PROTAC: ubiquitination databases record sites on it; its protein half-life has been measured.
Gene: Protein-coding gene on chromosome 5 (127,517,617 to 127,555,085, forward strand). Ensembl gene ENSG00000164244.
Subcellular location: Golgi apparatus; Cytoplasm
Subcellular location (Human Protein Atlas): Vesicles
Gene Ontology:
Molecular function: protein binding; protein kinase A regulatory subunit binding; identical protein binding
Biological process: epithelial structure maintenance
Cellular component: Golgi apparatus; cytoplasm
Genetic constraint (gnomAD): Loss-of-function variants: 25 observed, 30.65 expected, observed/expected ratio (o/e) 0.82, 90% interval 0.59 to 1.14. The upper end of that interval is the gene's LOEUF score, 1.14, which puts it in group 4 of 6, group 1 being the genes least tolerant of losing a copy. Missense variants: 503 observed, 510.13 expected, observed/expected ratio (o/e) 0.99, 90% interval 0.92 to 1.06. Synonymous variants: 157 observed, 184.43 expected, observed/expected ratio (o/e) 0.85, 90% interval 0.75 to 0.97.
Homologues: Orthologues: chimpanzee PRRC1 (99% identical), macaque PRRC1 (99% identical), rabbit PRRC1 (90% identical), guinea pig PRRC1 (88% identical), mouse Prrc1 (87% identical), dog PRRC1 (86% identical), rat Prrc1 (86% identical), pig PRRC1 (76% identical), tropical clawed frog prrc1 (69% identical), zebrafish prrc1 (66% identical), Caenorhabditis elegans C04G6.4 (20% identical).